SIRT1 (sirtuin 1)
Diseases named in the same sentence as SIRT1 in open-access papers (continued):
Sharing a sentence is not in itself a finding about the gene and the disease.
osteoarthritis (continued). "Thus, the estradiol-dependent and SIRT1-mediated inductions of autophagy (mitophagy in particular), associated with SIRT1-driven changes in the acetylation of autophagy-regulating factors, are responsible for antiaging effects in chondrocytes and may contribute to lower osteoarthritis morbidity." (PMID 37762053, 2023). "The miR-122 expression was significantly increased in osteoarthritis cartilage, while Sirt1 expression was significantly decreased." (PMID 35874275, 2022). "Recently, we also demonstrated that KMUP-1 reduces LPS-induced MAPKs and NF-κB activation in part through induction of SIRT1 in macrophage and protects against cartilage erosion in a rat model of osteoarthritis." (PMID 35571109, 2022). "We showed that 5 and 10 μM significantly increased the viability of chondrocytes isolated from osteoarthritis patients and activated Sirt1/AMPK/PGC‐1α signaling pathway." (PMID 34078001, 2021). "Our study for the first time identified a link between FA‐mediated osteoarthritis chondrocyte protection and SIRT1/AMPK/PGC‐1α signaling pathway and first showed involvement of reduced oxidative stress in this regulation." (PMID 34078001, 2021). "Consistently, we also found that inhibition of SIRT1 attenuated FA‐mediated protective effects against IL‐1β‐induced toxicity to osteoarthritis chondrocyte." (PMID 34078001, 2021). "MiR-122 targets SIRT1, and this axis is reported to regulate chondrocyte extracellular matrix degradation in the cartilage of osteoarthritis." (PMID 34943825, 2021). "The expression of miR-122 was increased in osteoarthritis cartilage compared to healthy controls, while SIRT1 expression was decreased." (PMID 34943825, 2021). "To determine the impact of FA on the Sirt1/AMPK/PGC‐1α signaling pathway in chondrocytes isolated from osteoarthritis patients, we first examined SIRT1 activity and found that FA dose‐dependently increased SIRT1 activity." (PMID 34078001, 2021). "Here, efforts in this study were made to unveil the specific role of SIRT1 in the therapy of acupuncture on cartilage degeneration in osteoarthritis (OA)." (PMID 35003293, 2021). "Metformin protects against IL-1β-induced extracellular matrix (ECM) degradation in cultured chondrocytes and in mouse osteoarthritis model through activating AMPKα/SIRT1 signaling." (PMID 32792951, 2020). "In osteoarthritis cartilage, research showed that the activation of SIRT1 is essential to the maintenance of articular cartilage homeostasis owing to its antiapoptotic effect." (PMID 31223428, 2019). "HTyr has the potential as a chondroprotective compound against osteoarthritis (OA), as an autophagy and sirtuin-1 (SIRT1) inducer." (PMID 31137753, 2019). "Previously we reported that melatonin had cytoprotective and anti-inflammatory effects on H2O2-induced cytotoxicity and inflammatory mediators in a model of human chondrocytes and rabbit osteoarthritis via the sirtuin 1 (SIRT1) pathway." (PMID 29895782, 2018). "Previous reports also showed the protective role of SIRT1 on the development of osteoarthritis by upregulation of cartilage extracellular matrix genes and downregulation of matrix-degrading enzymes." (PMID 30374331, 2018). "Consistently, low levels of SIRT1 were shown in human osteoarthritis subchondral osteoblasts, which were responsible for their abnormal mineralization." (PMID 30116472, 2018). "We then examined the therapeutic implications of our findings, and explored the therapeutic potential of blocking SIRT1 in preventing osteoarthritis triggered by DOT1L inactivation." (PMID 28627522, 2017).
osteoarthritis (continued). "The balance between DOT1L and SIRT1 activity determines the activation of Wnt signalling in cartilage, with excessive pathway activity resulting in osteoarthritis." (PMID 28627522, 2017). "Overall, our data demonstrate the importance of the DOT1L/SIRT1 axis in maintaining cartilage health and provides a rationale for potential therapeutic interventions in the treatment of osteoarthritis." (PMID 28627522, 2017). "A prior investigation uncovered a new mechanism through which SIRT1 exerts its anti-inflammatory effects, pinpointing SIRT1 regulation as a potential therapeutic strategy for preventing inflammation-related postoperative complications in osteoarthritis." (PMID 39857301, 2025). "In addition, metformin is known to activate the AMPK/SIRT1 signaling pathway, which plays a key role in the treatment of osteoarthritis." (PMID 40806700, 2025). "Our pilot study aimed to characterize the expression profile of cell cycle regulators, factors released by aged cells, and sirtuin 1 (SIRT1) in the muscle tissue of 26 elderly patients undergoing hip arthroplasty, including 13 with low-energy fracture and 13 with osteoarthritis (OA)." (PMID 40564069, 2025). "Interestingly, Zheng and colleagues demonstrated that fisetin exerts anti-inflammatory and chondroprotective effects in osteoarthritis through the activation of SIRT1." (PMID 40806700, 2025). "Research has also underscored quercetin’s capacity to mitigate mitochondrial dysfunction and promote biogenesis in osteoarthritis-afflicted rats by increasing the expression levels of SIRT1, PGC-1α, NRF1, NFR2, TFAM, and phospho-AMPKα, suggesting its action through the AMPK/SIRT1 pathway." (PMID 38474354, 2024). "Mechanistically, m6A modification up-regulates the expression of LINC00680 in the osteoarthritis tissue and interleukin-1β (IL-1β)-induced isolated primary chondrocytes, and the latter enhances the mRNA stability of SIRT1, a gene with definite functions in osteoarthritis." (PMID 38665846, 2024). "Similarly, surgically-induced osteoarthritis is accelerated in mice conditionally invalidated for SIRT1 in articular cartilage compared to wild type." (PMID 36733912, 2023). "It has been demonstrated that metformin can promote chondrocyte autophagy and reduce chondrocyte apoptosis through the AMPKα2/SIRT1 pathway to alleviate osteoarthritis, and the protective effect of metformin is reversed by silencing AMPKα2 or blocking SIRT1 expression." (PMID 37928155, 2023). "Given that MSC-released exosomal KLF3-AS1 regulates Sirt1 in osteoarthritis, whether MSC-derived exosomal KLF3-AS1 regulates Sirt1 in cerebral I/R injury need to be further explored." (PMID 36627572, 2023). "For example, proteolytic cleavage of SIRT1 induced by TNFα in osteoarthritis renders accumulation of a catalytically inactive 75 kDa resistant fragment that could be detected by immunohistochemistry." (PMID 37530744, 2023). "In addition, heterozygous mice for SIRT1 ± show more severe signs of osteoarthritis than SIRT1 +/+ mice with reduced expression of COL2A1 and ACAN." (PMID 36733912, 2023). "Based on these important findings, K33 or other lysine sites in Sirt6 may be deacetylated by Sirt1 in chondrocytes in the context of chondrocytes senescence and osteoarthritis." (PMID 36496445, 2022). "SIRT1 may aggravate osteoarthritis cartilage degeneration by activating the SREBP2 protein-mediated PI3K/AKT signaling pathway." (PMID 35812736, 2022). "Overexpression of silent information regulator 2 ortholog 1 (SIRT1) is associated with beneficial roles in aging-related diseases; however, the effects of SIRT1 overexpression on osteoarthritis (OA) progression have not yet been studied." (PMID 34639026, 2021).
osteoarthritis (continued). "Mechanistically, several studies have reported that fisetin can activate the SIRT1 (Sirtuin 1) signaling pathway in experimental models such as the osteoarthritis model, tunicamycin-mediated cell death in PC12 cells, lead-induced neurotoxicity, and aging-induced neurodegeneration." (PMID 35273493, 2021). "Our findings suggest that SIRT1 activity is involved in mediating the protective effects of FA against IL‐1β‐induced toxicity and inhibition of SIRT1 by Sirtinol significantly attenuated the suppressive effects on IL‐1β‐induced osteoarthritis chondrocyte degeneration." (PMID 34078001, 2021). "We examined the effects of FA on osteoarthritis chondrocyte viability and SIRT1 activation." (PMID 34078001, 2021). "Resveratrol, an activator of Sirt1, can increase the expression of Sirt1 to treat osteoarthritis." (PMID 33371243, 2020). "Importantly, in human femoral BM-MSCs obtained from female patients undergoing hip operations for fracture or osteoarthritis, Sirt1 activation by SRT3025 increased PGC1α mRNA and protein level." (PMID 30873124, 2019). "In addition, increase in the SIRT1 activity had a protective effect against osteoarthritis in animal models." (PMID 30374331, 2018). "SIRT1 activator resveratrol protects against osteoarthritis in the same model." (PMID 28627522, 2017). "Moreover, Fgf21, shown to alleviate senescence, apoptosis, and ECM degradation in osteoarthritis via the SIRT1‐mTOR signaling pathway, was upregulated in the agarose encased cells, together with Fgf1 and 2, markers of human fetal growth plate cartilage, and Fgfr3, a key regulator of chondrogenesis." (PMID 40415244, 2025). "Consequently, the SIRT1/Nrf2 signaling axis emerges as a critical pathway in maintaining chondrocyte integrity and attenuating the degenerative processes in the joint, offering a potential therapeutic strategy for managing osteoarthritis." (PMID 40109363, 2025). "Interleukin‐1β (IL‐1β) is involved in osteoarthritis pathogenesis and mediates a series of toxic processes including the production of matrix metalloproteinase and inflammatory regulators which are suppressed by activation of silent information regulator 1 (SIRT1)." (PMID 34078001, 2021). "Therefore, the investigators suggested that the increase both in the activity and expression of SIRT1 might be a protective strategy for progression of osteoarthritis via the modulation of the NF-κB pathway." (PMID 30374331, 2018). "Increased SIRT1 expression in chondrocytes reduces ATF4 expression and inhibits the PERK/eIF2α/CHOP pathway, thereby alleviating oxidative stress-induced osteoarthritis (OA)." (PMID 39857301, 2025). "Articular chondrocytes from MT-COMP/CHOP−/− mice displayed higher IL-10 and lower TNFα levels, which influenced key molecules such as SIRT1 and MMP-13, both critical to joint health and osteoarthritis progression." (PMID 39795874, 2024). "Therefore, Sirt1 could be a therapeutic target for osteoarthritis." (PMID 35874275, 2022). "Quercetin inhibited oxidative stress-induced apoptosis in rat chondrocytes via SIRT1/AMPK-mediated ER stress suppression and delayed the progression of osteoarthritis in a rat model." (PMID 35457176, 2022). "Quercetin suppressed oxLDL-induced mitochondrial dysfunction and ROS formation by activating SIRT1 and modulating the AMPK/NADPH/AKT pathway, and attenuate mitochondrial dysfunction via activating AMPK/SIRT1 pathway in osteoarthritis rats." (PMID 35935939, 2022). "Finally, as FA significantly enhanced the Sirt1/AMPK/PGC‐1α signaling pathway, we investigated whether suppression of SIRT1 activity by Sirtinol, a SIRT1 inhibitor, could abolish the protective effects of FA on IL‐1β‐induced degeneration of osteoarthritis chondrocytes." (PMID 34078001, 2021).
osteoarthritis (continued). "Recent studies have confirmed that QUE could alleviate osteoarthritis through regulating dysfunctional mitochondria or endoplasmic reticulum, which are involved in attenuating ROS levels and inhibiting chondrocyte apoptosis through upregulation of SIRT1 and phosphorylation of AMPK." (PMID 34055990, 2021). "To assess if SIRT1 fragments are affected by OA, we performed DMM surgery on wild-type (wt) mice (CD1/129/J) to induce post-traumatic osteoarthritis (PTOA) and we also compared young (3 months) and old (15 months) mice." (PMID 32665267, 2020). "Accumulating evidence indicates that SIRT1 has an important role in IDD and osteoarthritis (OA) pathogenesis." (PMID 30487517, 2018). "In osteoarthritis (OA), MCM3AP-AS1 level was detected to be reduced in OA cartilage tissues and shields chondrocytes from inflammation triggered by interleukin (IL)-1β by regulating the miR-138-5p/SIRT1 signaling pathway." (PMID 40181954, 2025). "In addition, some studies reported that the silent information regulator factor 2-related enzyme 1 (Sirt1), which belongs to the family of NAD+-dependent class 3, had a positive role in osteoarthritis by maintaining chondrocyte homeostasis." (PMID 38543230, 2024). "Additionally, ferulic acid, another HY-LL component, has been found to mitigate osteoarthritis chondrocyte toxicity by inhibiting the production of IL-6, PGE-2, and sub-MMP-9 and activating the SIRT1/AMPK/PGC-1α signaling pathway." (PMID 39337919, 2024). "In the context of osteoarthritis, MCM3AP-AS1 via modulating the miR-138-5p/SIRT1 axis could protect chondrocytes from IL-1β-induced inflammation." (PMID 37441551, 2023). "SIRT1, an NAD+-dependent deacetylase, is downregulated in RA compared to osteoarthritis." (PMID 37715217, 2023). "In summary, our study suggests that FA possesses powerful protective effects on IL‐1β‐induced osteoarthritis degeneration by preventing ECM degradation, suppressing inflammation responses, and inhibiting oxidative stress through regulation of the Sirt1/AMPK/PGC‐1α signaling pathway." (PMID 34078001, 2021). "Thus, we discovered that modulation of SIRT1 activity is a leading mechanism by which DOT1L controls activation of Wnt signalling, maintains cartilage health and prevents osteoarthritis." (PMID 28627522, 2017). "Taken together, our present findings firstly indicate that curcumin could inhibit the PERK-eIF2α-CHOP axis of the ER stress response through the activation of SIRT1 in tert-Butyl hydroperoxide- (TBHP-) treated rat chondrocytes and ameliorated osteoarthritis development in vivo." (PMID 31223428, 2019). "Specifically, in a study to develop a therapeutic strategy for osteoarthritis, Que was shown to increase expression levels of SIRT1, PGC-1α, NRF1 and NFR2, TFAM, and phospho-AMPK α in osteoarthritis rats, confirming the hypothesis that Que might act via the AMPK/SIRT1 signaling pathway." (PMID 32848804, 2020). "Although the expression of SIRT1 in human IVD cells has not yet been established, SIRT1 has recently been found to be expressed by human chondrocytes and to play a key role in chondrocyte survival by regulating apoptosis, findings that could be important in the pathogenesis of osteoarthritis." (PMID 22152608, 2011).
liver fibrosis (88 papers, 2016 to 2026). "The SIRT1/Nrf2 pathway has been implicated in the management of oxidative stress in liver fibrosis; however, improvements in targeting metabolic pathways have also focused on glucose regulation, particularly through sodium‐glucose cotransporters (SGLTs)." (PMID 41498016, 2025). "TAA administration is known to induce liver fibrosis through the ablation of SIRT1 activity, which is associated with deactivated AMPK." (PMID 40943413, 2025). "By regulating pathways associated with aging, SIRT1 affects the development of various liver conditions, including liver fibrosis, ALD, MAFLD, MASH, and HCC." (PMID 40052151, 2025). "GEN improved schistosomiasis-induced liver fibrosis associated with strong elevation of sirtuin 1 (SIRT1) expression and activity." (PMID 39512816, 2024). "To elucidate the possible mechanism underlying age‐related liver fibrosis, we found that hepatic levels of the longevity factor SIRT1 declined dramatically by ~70% with age, mimicking the inhibitory effect of CCl4 administration on SIRT1." (PMID 36999514, 2023). "It would be of interest to further define the in vivo mechanistic role of FGF21 in liver fibrosis associated with SIRT1 loss during aging." (PMID 36999514, 2023). "One of our most important findings is that age‐dependent susceptibility to liver fibrosis is likely attributed to impaired SIRT1 signaling in hepatocytes." (PMID 36999514, 2023). "Our in vivo data suggest that anti-miR-132 treatment reversed the inhibition of SIRT1 and caused an overall improvement in liver fibrosis phenotype." (PMID 34458001, 2021). "To validate the possible underlying mechanism of GF on TAA-injected hepatic fibrosis, we focused on the epigenetic regulator, SIRT1 which is well known for a NAD+, NADH-dependent class III protein deacetylase-enzyme." (PMID 34829709, 2021). "Collectively, the SIRT1/C/EBPα axis and bile acid metabolism may be linked to the progression of arsenic-induced liver fibrosis." (PMID 42278648, 2026). "This study established time-dependent rat models of arsenic-induced liver fibrosis with resveratrol intervention to investigate the potential association between SIRT1, bile acid metabolic disturbance, and liver fibrosis, as well as resveratrol's hepatoprotective effects." (PMID 42278648, 2026). "Importantly, middle-aged mice were more susceptible to greater liver fibrosis after long-term chronic plus multiple binges (via downregulation of SIRT1)." (PMID 38699545, 2024). "Our studies indicate that the longevity factor SIRT1 is implicated in metabolic disease; however, whether and how hepatocyte‐specific SIRT1 signaling is involved in liver fibrosis remains undefined." (PMID 36999514, 2023). "Given the evidence that inhibition of SIRT1 is linked to excessive ECM deposition in old mice within the context of liver injury, we sought to determine the role of hepatocyte SIRT1 loss in liver fibrosis by using hepatocyte‐specific SIRT1 knockout (SIRT1 LKO, AlbCre+SIRT1f/f) mice." (PMID 36999514, 2023). "Interestingly, SIRT1 is downregulated during organ injury and aging-associated fibrosis, which means SIRT1 can also be a new therapeutic target in liver fibrosis." (PMID 34887768, 2021). "Hence, these results confirmed that in the process of CCl4‐induced defenestration in HSECs and liver fibrosis, oxidative damage triggered progerin‐associated premature senescence, with the decrease of SIRT1‐mediated deacetylation." (PMID 33522656, 2021). "In addition, HSC-specific SIRT1 knockout mice were more susceptible to ethanol-induced liver fibrosis with upregulation of alpha-smooth muscle actin (α-SMA), platelet derived growth factor (PDGF) and Collagen alpha-1(V) chain (Col5a1) mRNA levels." (PMID 33162823, 2020). "SIRT1 is a key metabolic regulator and promising therapeutic candidate, while its role in bile acid metabolism during arsenic-induced liver fibrosis remains poorly defined." (PMID 42278648, 2026).